RN7SL720P (RNA, 7SL, cytoplasmic 720, pseudogene)
Gene: Miscellaneous RNA gene on chromosome 9 (17,053,901 to 17,054,204, forward strand). Ensembl gene ENSG00000241152.
Homologues: Orthologues: chimpanzee Metazoa_SRP (98% identical). Paralogues in human: RN7SL1 (82% identical), RN7SL2 (82% identical), RN7SL3 (81% identical), RN7SL122P (78% identical), RN7SL126P (78% identical), RN7SL127P (78% identical), RN7SL665P (78% identical), RN7SL357P (78% identical), RN7SL147P (77% identical), RN7SL220P (77% identical), RN7SL44P (77% identical), RN7SL464P (77% identical), and 698 more.